HSF1 (heat shock transcription factor 1)
Diseases named in the same sentence as HSF1 in open-access papers (continued):
Sharing a sentence is not in itself a finding about the gene and the disease.
breast cancer (continued). "We have reported that HSF1 regulates β-catenin RNA, which contains many AU-rich sequences, in mammary cancer cells by controlling HuR/ElavL1 expression." (PMID 36982267, 2023). "Another study investigated FAM3C activation of HSF1, which promoted the growth and motility of breast cancer cells." (PMID 37958341, 2023). "In breast cancer cells, HSF1 and ErbB2 (HER2) work together to promote glycolysis, cell migration, and invasion." (PMID 37958341, 2023). "The supportive role of HSF1 for the cancer stem cell (or stem cell-like) phenotype was already demonstrated in breast cancer, melanoma, gynecological cancer and acute myeloid leukemia." (PMID 37894333, 2023). "Our previous work indicated that HSF1 can be activated by AKT1 via phosphorylation at S326 in breast cancer cells." (PMID 35080342, 2022). "Consistent with the observed inverse relationship between HSF1 and EGR4-S, the knockdown of HSF1 in Hs578T basal breast cancer cells, which have high endogenous HSF1 protein levels, was associated with the higher expression of EGR4-S." (PMID 35326716, 2022). "Surprisingly, we found a widespread amplification and overexpression of the protein-coding genes between the GSDMD and HSF1 in breast cancer." (PMID 36497066, 2022). "In breast cancer cells, phosphorylation of heat-shock transcription factor 1 (HSF1) at Thr120 by PIM2 promotes its stability and activates HSF1-induced PD-L1 expression." (PMID 36429128, 2022). "While most patients with stage I breast cancer had low HSF1 expression, at more advanced stages elevated HSF1expression was more common." (PMID 35311075, 2022). "Since we had observed the inverse association between HSF1 and EGR4-S in HER2+ cancer cells across several experimental conditions, we decided to examine the effect of directly manipulating EGR4 and HSF1 levels on breast cancer cells." (PMID 35326716, 2022). "We then treated CGL2 or MDA-MB-231 breast cancer cells with each anti-mitotic drug plus the indicated HSF1 inhibitor and found that the combined treatment significantly reduced the cell viability compared to anti-mitosis drug alone or HSF1 inhibitor alone." (PMID 34922589, 2021). "Taken together, we are proposing a mechanism where high HSF1 levels interfere with the ERα-dependent transcriptional program leading to endocrine resistance in breast cancer." (PMID 33593922, 2021). "E2-activated HSF1 is transcriptionally potent and takes part in the regulation of several genes essential for breast cancer cell growth." (PMID 34783649, 2021). "S363 phosphorylation of HSF1 was remarkably increased in breast cancer and colon cancer, but decreased in UCEC tissues compared to normal adjacent tissues." (PMID 34239690, 2021). "Accordingly, numerous genes regulated by HSF1, including HSPD1, HSPH1, and HSP90AA1, are also associated with poor prognosis for breast cancer patients." (PMID 33593922, 2021). "In this regard, it has recently been found that in breast cancer models HSF1 recruits PARP1 through the damage regulator PARP13, thus forming a ternary complex." (PMID 34198675, 2021). "The experiments revealed that breast cancer cells with lower levels of HSF1 also had lower levels of ERα and responded less well to estrogen than cells with higher levels of HSF1." (PMID 34783649, 2021). "PIM2-regulated phosphorylation of HSF1 at Thr120 facilitated breast cancer oncogenesis in vivo and in vitro." (PMID 34239690, 2021). "The levels of phosphorylation of S363 in HSF1 were significantly enhanced in breast cancer, ovarian cancer, and colon cancer compared to normal adjacent tissues." (PMID 34239690, 2021). "The phosphorylation of AKT at S473 and the phosphorylation of HSF1 at S326 were highly related to a shortened time to metastasis in breast cancer." (PMID 34239690, 2021).
breast cancer (continued). "Here we show that HSF1 overexpression was sufficient to degrade ERα and initiate antiestrogen resistance in breast cancer cells." (PMID 33593922, 2021). "Taken together, our results provide a proof-of-concept that inhibition of HSF1 in combination with antiestrogens is a promising combinatorial therapeutic approach for ERα-positive endocrine-resistant breast cancers." (PMID 33593922, 2021). "Nevertheless, the observed features of gene expression profiles confirmed collectively that HSF1 affects the genomic action of ERα in breast cancer." (PMID 34783649, 2021). "(D) Gene set enrichment analyses showing differences between ER+ and ER− breast cancers with different HSF1 levels." (PMID 34783649, 2021). "S307 phosphorylation of HSF1 was increased in breast cancer and colon cancer tissues compared to normal tissues." (PMID 34239690, 2021). "Previously, we have found that the major female sex hormone 17β-estradiol (E2) stimulates activation of heat shock factor 1 (HSF1) in estrogen-dependent breast cancer cells via MAPK signaling." (PMID 34783649, 2021). "Last, our results establish a proof of concept that inhibition of HSF1, in combination with antiestrogens, is a valid strategy to tackle resistant breast cancers." (PMID 33593922, 2021). "In breast cancer, Akt mediates the phosphorylation of HSF1, which stimulates the expression of Slug and triggers the EMT." (PMID 34198675, 2021). "KNK437 was demonstrated to act as a radiosensitizer toward breast carcinoma cells and glioblastoma cells undergoing hypoxia, but the researchers indicated an HSF1-independent mechanism of the radiosensitization." (PMID 33806538, 2021). "The oncogenic function of HSF1 is also observed in osteosarcoma, breast cancer, colon, melanoma, and pancreatic cancer." (PMID 32691951, 2020). "More recently, it has been shown that HSF1 is abundant in the nuclei of mammary tumor cells in clinical biopsy samples, indicating constitutive activation of the heat shock response in cancer." (PMID 32331382, 2020). "Distinct signaling proteins such as heat shock factor 1 (HSF1), TGF-β and CXCL12 have been implicated in transformation of stromal cells in breast cancer." (PMID 33096815, 2020). "A key signaling nexus in breast cancer is the receptor tyrosine kinase HER2, also called ERBB2, which is upregulated in 25% of breast cancer cases and promotes metastasis, partially by activating HSF1." (PMID 32408596, 2020). "To date, several studies have characterized supportive oncogenic function for HSF1 in breast cancer, and multiple mechanisms contributing to HSF1 activation have been proposed." (PMID 32408596, 2020). "The prominent role of HSF1 has been observed in several cancers, including gastric cancer, osteosarcoma, breast cancer, and esophageal squamous cell carcinoma." (PMID 32943987, 2020). "HSF1 activation in HER2-positive breast cancer depends on the ability of HER2 to constitutively stimulate phosphorylation of HSF1 at serine 326 by protein kinase B (PKB), also called AKT." (PMID 32408596, 2020). "TICs sorted from the tumor population in MMT murine breast cancer were found to be enriched in activated HSF1 phosphorylated at S326 as well as in downstream products, such as Hsp72 and MTA1." (PMID 32331382, 2020). "Surprisingly, a recent report showed that HSF1 activity is high in HER2-positive breast cancer cells that are resistant to Lapatinib, a drug used to inhibit HER2." (PMID 32408596, 2020). "Loss of Hsf1 in MEFs impeded ECM deposition induced by MC38 colon cancer-conditioned media and 4T1 breast cancer-conditioned media." (PMID 33288768, 2020). "Breast carcinomas have been shown to overexpress HSF1, and in this cancer type the HSF1-CaSig in patient samples is strongly associated with metastasis and death." (PMID 32408596, 2020).
breast cancer (continued). "E2­activated HSF1 was transcriptionally potent and several genes essential for breast cancer cells growth and/or ERα action, including HSPB8, LHX4, PRKCE, WWC1, and GREB1, were activated by E2 in a HSF1-dependent manner." (PMID 31614463, 2019). "Downstream of TGF-β signaling YY1 enhances HSF1 expression and promotes proliferation and migration of breast cancer cells." (PMID 31824839, 2019). "An increase in FAM3C expression due to excessive TGFβ production plays important roles in inducing YY1 and HSF1 expressions as observed in human breast cancer or other cancer tissues." (PMID 30887707, 2019). "Overall, these findings revealed that FAM3C stimulated the proliferation and migration of breast cancer cells by activating HSF1‐Akt pathway." (PMID 30887707, 2019). "FAM3C inhibition repressed TGFβ‐induced HSF1 activation, and proliferation and migration of breast cancer cells." (PMID 30887707, 2019). "In fact, the increased expression and activity of HSF1 are observed in a variety of cancers, such as prostate and breast cancers, in advanced stages, suggesting HSF1 as an important regulator of tumor progression and metastasis." (PMID 31878360, 2019). "YY1 silencing blunted FAM3C‐ and TGFβ‐triggered activation of HSF1‐Akt‐Cyclin D1 pathway, and proliferation and migration of breast cancer cells." (PMID 30887707, 2019). "Looking for the cross-talk between estrogen and HSF1 signaling pathways we found that E2 can activate HSF1 in ERα-positive breast cancer cells through MEK1/2 signaling." (PMID 31614463, 2019). "Overall, these findings revealed that HSF1 is a direct target gene of YY1, which stimulated the proliferation and migration of breast cancer cells by inducing HSF1 expression." (PMID 30887707, 2019). "Clearly, the roles of FAM3C, YY1 and HSF1 in the pathogenesis of breast cancer and/or other cancers should be considered as a whole." (PMID 30887707, 2019). "FAM3C activates YY1 to induce HSF1 expression, which finally triggers the proliferation and migration of breast cancer cells by activating Akt." (PMID 30887707, 2019). "The inhibition of HSF1 led to the decreased breast cancer formation and lung metastasis in a mouse model." (PMID 31878360, 2019). "YY1 was shown to directly activate HSF1 transcription to promote the proliferation and migration of breast cancer cells." (PMID 30887707, 2019). "FAM3C up‐regulates YY1 to induce HSF1 expression, finally activating Akt‐Cyclin D1 pathway to promote the proliferation and migration of breast cancer cells." (PMID 30887707, 2019). "The effects of suppressing the function of HSF1 in cancer types such as breast cancer, colorectal cancer, and leukemia have been examined." (PMID 31878360, 2019). "We documented that estrogen (as well as xenoestrogens) through ERα and MAPK can activate HSF1 in breast cancer cells." (PMID 31614463, 2019). "In summary, this study revealed that FAM3C, YY1 and HSF1 are coordinated to promote the proliferation and migration of human breast cancer MDA‐MB‐231 cells." (PMID 30887707, 2019). "A high level of HSF1 in estrogen receptor (ER)-positive breast cancer patients correlated with a worse prognosis." (PMID 31614463, 2019). "Our results show that HSF1 gene expression is elevated in breast cancer tissue and two of the studied SNPs correlate significantly with cancer development." (PMID 29494616, 2018). "Quantitative analysis showed that the increase in ratio of phosphorylated HSF1 to total HSF1 after NVP-AUY922 treatment correlates with the resistance of breast cancer cell lines to Hsp90 inhibition (r = 0.718; p = 0.0161)." (PMID 30138434, 2018). "Qualitative levels of HSF1 were determined by immunohistochemistry to identify the interaction between HSF1 and breast cancer to correlate HSF1 expression and selected polymorphic sites with the clinical presentation in Saudi females." (PMID 29494616, 2018).
breast cancer (continued). "We retrieved levels of HSF1-regulated chaperones for the studied breast cancer lines and compared with relative sensitivity." (PMID 30138434, 2018). "In this regard, it has also been demonstrated that HER2/Erb2 overexpression in breast cancer controls the major oncogenic growth factor HSF1, that also regulates the fate of HSP90 and its clients." (PMID 29707160, 2018). "Our data suggest a mechanism-based rationale for the clinical utilization of HSF1 inhibitors for the treatment of lapatinib-resistant ERBB2-positive breast cancer and/or—in combination with lapatinib—to prevent development of lapatinib resistance." (PMID 29799521, 2018). "These preliminary results show that the genotypes of SNPs in HSF1 do influence disease presentation of breast cancer." (PMID 29494616, 2018). "The HSF1 protein expression was higher in all invasive and in situ breast carcinoma compared to the normal tissue." (PMID 29494616, 2018). "On the other hand, the present study showed a high HSF1 protein expression in all invasive and in situ breast carcinoma while the expression was at a lower level in the normal tissue." (PMID 29494616, 2018). "Our results indicate combining AKT inhibition with HSF1 inhibition is strongly synergistic in multiple breast cancer cells with different genetic and subtype backgrounds." (PMID 29088759, 2017). "To this end, we assessed the endogenous activation of AKT and HSF1 in a panel of breast cancer cells from each major subtype and normal breast epithelial cells." (PMID 29088759, 2017). "Our observations also indicate that dual inhibition of AKT and HSF1 was synergistic in killing breast cancer cells from multiple subtypes in vitro and significantly reduced tumor growth and time to metastasis in vivo." (PMID 29088759, 2017). "Our lab recently added to this list by showing HSF1 promotes EMT in HER2-positive breast cancer by direct upregulation of Slug." (PMID 29088759, 2017). "Herein, we showed AKT and HSF1 to be frequently co-activated in breast cancer cell lines and specimens across different subtypes." (PMID 29088759, 2017). "It is notable that HSF1 in mammary cancer stem cells, the cells that govern tumorigenicity, invasion and metastasis, is constitutively phosphorylated on serine 326 and dephosphorylated on serine 303, suggesting a causal role for activated HSF1 in stemness." (PMID 28484363, 2017). "In breast cancer HSF1 repression can be relieved by exposure to the ligand heregulin that binds cell surface receptor tyrosine kinase HER3." (PMID 28484363, 2017). "Several studies have demonstrated that HSF1 is activated and predicts a poor prognosis in various types of cancer, including breast cancer, colon cancer, and liver cancer." (PMID 28783244, 2017). "Taken together, these data suggest that AKT and HSF1 are frequently co-activated in breast cancer cell lines and breast cancer patient specimens across subtypes and this co-activation is not restricted to any one particular subtype." (PMID 29088759, 2017). "Our results further add to the scope of HSF1 function in breast cancer as we observed activity of HSF1 in all major subtypes and this activity is associated with poor patient outcomes." (PMID 29088759, 2017). "We further observed enhanced AKT and HSF1 activation in breast cancer stem cells, which are thought to mediate metastasis to distant organs." (PMID 29088759, 2017). "Highly malignant mammary cancer stem cells contain very low levels of the GSK3 target HSF1-phospho-S303, consonant with the findings of that levels of Hsp70 are required for stemness." (PMID 28484363, 2017). "The finding that AKT can directly phosphorylate and activate HSF1 is important considering the pervasive PI3K-AKT activity in breast cancer." (PMID 29088759, 2017).
breast cancer (continued). "Our data suggests that AKT and HSF1 are co-activated in cells and tumors spanning all breast cancer subtypes." (PMID 29088759, 2017). "Many studies have shown that HSF1 is highly expressed and closely related to tumorigenesis and progression in malignancies such as human primary liver cancer, breast cancer, and melanoma." (PMID 28482903, 2017). "Our data further suggest AKT and HSF1 inhibition is synergistic in killing breast cancer cells and reducing tumor growth, overall survival, and time to develop metastasis in vivo." (PMID 29088759, 2017). "In a recent study involving a cohort of 1800 breast cancer patients, HSF1 expression was found to be low and cytoplasmic in normal mammary epithelial cells, whereas HSF1 expression was predominantly nuclear in the malignant tissues suggesting activation." (PMID 28914774, 2017). "A subsequent study revealed that in breast cancer cell lines, the overexpression of HSF1 induced an augmentation of the cancer stem cell markers and conferred resistance to chemotherapeutic drugs." (PMID 28783244, 2017). "Several studies have found that HSF1 is overexpressed in several cancer types including breast cancer, hepatocellular carcinoma, and colorectal cancer among others." (PMID 29088759, 2017). "Other cancers with high HSF1 mRNA levels include liver cancer, head and neck cancer, and breast cancer." (PMID 27997575, 2016). "Previous studies have shown that HSF1 promotes EMT in breast cancer cells through a mechanism that requires HER2." (PMID 27997575, 2016). "It was reported that HuR is activated through the PI3K/AKT/NF-κB pathway in gastric cancers and through the mTOR/HSF1 pathway in breast cancer cells." (PMID 27166258, 2016). "The nature of HSF1 upregulation needs to be validated in different cohorts to further validate its prognostic utility in breast cancer." (PMID 27713164, 2016). "A number of studies suggest that the Her2/EGFR2/Neu signaling pathway is an important activator of HSF1, at least in breast cancer." (PMID 25954247, 2015). "HSF1 activation in the stromal cells correlated strongly with poor outcome in both lung and breast cancer." (PMID 26511079, 2015). "Our data were in line with other studies in which high levels of HSF1 expression in the nucleus of several types of cancer, such as breast cancer, melanoma and hepatocellular carcinoma, was associated with reduced survival." (PMID 26511079, 2015). "To elucidate the physiological role of HSF1 in tumorigenesis, we examined the relationship between HSF1 expression and tumor malignancy in spontaneously induced rat mammary tumors." (PMID 26359349, 2015). "Clinically, the presence of high levels of nuclear HSF1 in Her2-positive mammary tumors correlates with poor patient prognosis." (PMID 25954247, 2015). "Rat mammary tumors derived using dimethylbenz(a)anthracence revealed that high levels of HSF1 expression which correlate with aggressive malignancy, interfered with the binding of Ku70-Ku80." (PMID 26359349, 2015). "Impairment of angiogenesis was observed also in the xenograft model using human breast cancer cells with HSF1 depletion." (PMID 24467529, 2014). "In MCF7 breast cancer cells selected for doxorubicin resistance an opposite effect was observed: HSF1 and HSPB1 expression was diminished." (PMID 24467529, 2014). "A high HSF1 expression was also detected in colorectal cancer, breast cancer, oral squamous cell carcinoma, hepatocellular carcinoma, multiple myeloma, glioma, and ovarian tumors." (PMID 24467529, 2014). "In breast cancer, HSF1 knockdown inhibited Erb2-induced breast tissue tumorigenesis and tumor metastasis in mouse models." (PMID 25199534, 2014). "The mean vessel area in ERBB2-induced breast cancer tumors was in Hsf1-/- mice almost twice as small as in wild type animals." (PMID 24467529, 2014).